VEGFA (vascular endothelial growth factor A)
Diseases named in the same sentence as VEGFA in open-access papers (continued):
Sharing a sentence is not in itself a finding about the gene and the disease.
asthma (157 papers, 2005 to 2025). "There are other miRNAs associated with the pathology of asthma and allergies, such as miR-21, which targets IL-12p35 in steroid-resistant asthma; miR-1248, which targets IL-5; and miR-15a, which inhibits VEGFA in CD4 + cells." (PMID 37605155, 2023). "In the pediatric population, the polymorphism for VEGFA-rs2146323AA was associated with a significantly reduced risk (p = 0.03) for wheezing and in asthma development." (PMID 37189993, 2023). "Previously, different SNPs were associated with lung function in population-based and asthma cohorts along time, suggesting a role of VEGFA variants in lung function and one of them, rs3025028, was also associated with the ratio of the active and inhibitory isoforms of VEGF-A165." (PMID 27163696, 2016). "The VEGFA is a key gene in asthma development that codes for vascular endothelial growth factor (VEGF) that regulates Th2-mediated inflammation through airway remodeling and blood vessel permeability." (PMID 39766875, 2024). "Previous studies have indicated that lower concentrations of miR-15a lead to the decreased expression of vascular endothelial growth factor A (VEGFA), an entity found to be over-expressed in the sputum and serum of patients with asthma." (PMID 38279356, 2024). "TNF, VEGFA and IL-18 were the other top targets identified to be explored for therapeutic benefit in asthma but need further clinical testing." (PMID 37735578, 2023). "The tested compound alleviates asthma symptoms in mice by suppressing HIF-1α/VEGFA-mediated M2 macrophage skewing." (PMID 37174726, 2023). "The vascular endothelial growth factor-A and its family is crucial for endothelial cell survival and angiogenesis and its components are known biomarkers for asthma-COPD overlap syndrome." (PMID 33468710, 2021). "There are extensive studies focusing on the relation among EGFR, VEGFA and asthma pathophysiology, which describe airway remodeling, airway hypermucus secretion, as well as immunological responses of airway inflammation." (PMID 33968984, 2021). "Stimulation with exosomes from asthmatic eosinophils also enhances CCR3 and VEGFA gene expression: CCR3 activation initiates proliferation through the MAPK cascade, while VEGFA is associated with bronchial wall remodeling, a characteristic of asthma." (PMID 40722500, 2025). "Notably, three common target genes—cyclin D1 (CCND1), vascular endothelial growth factor A (VEGFA), and glycogen synthase kinase-3 beta (GSK3B)—were identified as being regulated by all three miRNAs within pathways associated with asthma and inflammation." (PMID 38279356, 2024). "VEGFA significantly correlated with allograft rejection, aminoacyl-tRNA biosynthesis, asthma, autoimmune thyroid disease, autophagy-other, graft-versus-host disease, N-Glycan biosynthesis, propanoate metabolism, pyruvate metabolism, and staphylococcus aureus infection." (PMID 38830963, 2024). "A recent review has compiled data describing that individuals with asthma may be predisposed to features of airway remodeling based on single nucleotide polymorphisms in remodeling-associated genes, including IL13, PLAUR, VEGFA, and CHI3L1." (PMID 37773065, 2023). "This disparity in VEGFA expression between the sexes in the presence of maternal asthma further suggests an increased placental reserve capacity for female placentae and a reduced overall need for female-specific adaptations in the presence of severe maternal complications." (PMID 34203717, 2021). "In mouse model of asthma, Descurainia sophia seeds extract also downregulated VEGFa." (PMID 34400939, 2021). "VEGFA is a major regulator of angiogenesis and enhancer of vascular permeability, and seems to induce airway inflammation and airway remodelling in patients with asthma." (PMID 25326706, 2014).
asthma (continued). "A study focused on S100A4 protein and its connection to airway inflammation, epithelial barrier dysfunction and release of TH2 by VEGFA/VEGFR2 pathway, showing that increased secretion of this alarmin is related to the development of asthma." (PMID 40723867, 2025). "In our study, we employed a network pharmacology approach to prioritize seven predicted targets (AKT1, VEGFA, EGFR, SRC, MAPK3, MMP9, MAPK1) of baicalein for asthma treatment, and confirmed its high binding affinity to these targets through molecular docking." (PMID 38178132, 2024). "We identified HMOX1, ITGAM, SFTPD and ADAM17 as the top novel targets for asthma which need to be validated experimentally whereas IL-18, TNF and VEGFA as the strongest therapeutic targets to investigate further for clinical benefit." (PMID 37735578, 2023). "For the molecular docking, the four target genes, AKT1, EGFR, VEGFA, and HSP90AB, were selected based on KEGG analysis results in the asthma pathway." (PMID 36836768, 2023). "IL6, IL-1β, TNF, VEGFA, AKT1, etc., played an essential role in the PPI network, indicating the crucial roles in treating asthma and IPF." (PMID 35672815, 2022). "We used an OVA-induced asthma mouse model to verify that the expression of VEGFA, EGFR and the phosphorylation of ERK are involved in the pathogenesis of asthma, and that baicalein can inhibit the expression of VEGFA, EGFR and the phosphorylation of ERK in these mice." (PMID 38178132, 2024). "Finally, we obtained 7 predicted targets of baicalein for asthma treatment, namely AKT1, VEGFA, EGFR, SRC, MAPK3, MMP9, MAPK1." (PMID 38178132, 2024). "Further validation by reverse transcription quantitative polymerase chain reaction (RT-qPCR) and western blotting analysis revealed that the VEGF and EGFR signaling pathways involving VEGFA, MAPK1, MAPK3, and EGFR were inhibited by baicalein in the asthma mouse model." (PMID 38178132, 2024). "Our subsequent molecular docking showed that each bioactive compounds (quercetin, wogonin, luteolin, naringenin, and kaempferol) of MGMD has favorable binding abilities with STAT3, PTGS2, JUN, VEGFA, EGFR, and ALOX5, further arguing the potential molecular mechanism of action of MGMD in asthma." (PMID 33968984, 2021).
Nephropathy (156 papers, 2009 to 2026). A nonspecific term referring to disease or damage of the kidneys. "Cancer is the disease that is most commonly linked to AS dysregulation; however, there are an increasing number of splice isoforms that have been recently implicated in kidney disease, including vascular endothelial growth factor A (VEGF-A)." (PMID 29462869, 2018). "Renal diseases are frequently associated with impaired angiogenesis, capillary loss, and a reduction of VEGFA expression." (PMID 28774305, 2017). "Insight from this study could potentially mean that some of the drugs that are used for treatment of kidney diseases involving VEGFA and RHEB may potentially increase the risk of developing T2D among Africans." (PMID 40524645, 2025). "We also found, using the Olink proteomic platform, that TNF-α and TMAO enhanced the secretion of additional inflammatory-and growth mediators associated with kidney disease; VEGFA, GDNF, CDCP1, OPG, uPA, AXIN1, MMP-1, MMP-10, PD-L1, HGF, Flt3L, 4E-BP1, CD40, CASP-8, ADA, TNFRSF9, TWEAK44–61." (PMID 38643262, 2024). "VEGFA is associated with 4 complications: nephropathy, neuropathy, retinopathy and atherosclerosis." (PMID 28761062, 2017). "Consistently, our data show that VEGFA and VEGFR2 are significantly reduced in the glomeruli of Sirt3-deficient mice, even prior to kidney damage induction." (PMID 37816025, 2023). "The findings of this study indicate that NGR1 has the potential to mitigate kidney disease and exert regulatory effects on VEGFA, F2R, and FGF1." (PMID 37415174, 2023). "In recent decades, studies that investigated dysregulation of VEGFA expression during kidney diseases have led to the identification of a crucial role of this proangiogenic factor in the renal capillary network." (PMID 36114523, 2022). "Furthermore, NS disrupts some DM complications such as nephropathy through upregulation of vascular endothelial growth factor-A (VEGFA) and transforming growth factor-β (TGF-β1)." (PMID 34833928, 2021). "In the podocytes of FSGS, elevated expression of microRNA-193a reduced WT1 expression and thereby downregulated target genes of WT1 that are vital to podocyte structure, including PODXL (podocalyxin), NPHS1 (nephrin), VEGFA (VEGFA), etc., eventually leading to kidney disease and proteinuria." (PMID 33921219, 2021). "The present study has demonstrated a molecular interaction between VEGFA and FGF1, which serves a protective function in the progression of renal diseases." (PMID 37415174, 2023). "Vascular endothelial growth factor A (VEGFA) is the key mediator of angiogenesis, which leads to numerous kidney diseases." (PMID 36114523, 2022). "This research showcases the dysregulation of lncH19, miR-29b, and VEGFA circulating levels in diabetic individuals with and without nephropathy compared to controls within a population from the “Middle East” region." (PMID 39852135, 2024). "In recent years, with the use of vascular endothelial growth factor A (VEGFA) inhibitors in oncology, the number of patients with kidney disease has increased, mainly manifesting as thrombotic microangiopathy, minimal change nephropathy, and collapsing focal segmental glomerulosclerosis." (PMID 36114523, 2022). "However, urinary VEGFA levels, measured by ELISA, were significantly increased in patients with active LN compared with active SLE patients without renal disease and healthy controls (p = 0.01 and p < 0.0001, respectively)." (PMID 31533337, 2019).
Sepsis (147 papers, 2007 to 2026). Sepsis is defined as life-threatening organ dysfunction caused by a dysregulated host response to infection. "TNF-related apoptosis-inducing ligand levels (TRAIL) (OR = 1.094, 95%CI = 1.012 ~ 1.183, P = 0.025) and vascular endothelial growth factor A levels (VEGF-A) (OR = 1.182, 95%CI = 1.016 ~ 1.375, P = 0.031) were associated with an increased risk of sepsis." (PMID 39176264, 2024). "According to the MR analysis, we found that C-C motif chemokine 19 (CCL19), C-C motif chemokine 28 (CCL28), TNF-related apoptosis-inducing ligand (TRAIL), and vascular endothelial growth factor A (VEGF-A) levels were associated with an increased risk of sepsis-related outcomes." (PMID 39176264, 2024). "Furthermore, TASE decreased the HIF-1α pathway-associated genes IRAK-M, VEGFA and PD-L1 in sepsis cells, suggesting HIF-1α inhibition by TASE leads to higher cytokine production in these cells as a consequence of IRAK-M downregulation." (PMID 37047205, 2023). "The expression of SLC31A1, CD274, ATOX1, MTF1, UBE2D1, DLD, and VEGFA was found to be upregulated, while that of DLST, UBE2D2, COX11, DLAT, GLS, FDX1, and ULK2 were significantly downregulated in patients with sepsis-associated ALI." (PMID 38779731, 2025). "Despite not presenting an association with any outcome, we showed that all studied genes, except VEGFA, positively correlated on admission in patients who developed sepsis." (PMID 37367740, 2023). "This network demonstrated an upregulating effect of miR-125b-5p on SORT1 and GRN, and identified vascular endothelial growth factor A (VEGFA) as a possible target of GRN in sepsis." (PMID 34476621, 2021). "First, both miR-15a and miR-27a are known to or are predicted to target and inhibit genes that increase vascular permeability in the setting of sepsis including VEGFA, VEGFC and MYLK." (PMID 26683209, 2015). "Recent evidence supports that the excessive release of VEGFA from pulmonary vascular endothelial cells could be associated with the development of non-cardiogenic pulmonary edema in sepsis-associated lung injury." (PMID 37367740, 2023). "The aim of this study was to investigate the gene expression profile of HIF1A, ISG15, HK2, LDHA, HMOX1, EPO, and VEGFA under the setting of sepsis and septic shock, and furthermore to evaluate whether any of these molecules has potential value as a prognostic factor." (PMID 37367740, 2023). "Except for enzymes contributing to metabolic pathways, under hypoxia, HIFs regulate several genes with central roles in sepsis, including heme oxygenase-1 (HMOX1), erythropoietin (EPO), and the vascular endothelial growth factor (VEGFA)." (PMID 37367740, 2023). "Considering the importance of this pathway for sepsis and ferroptosis, we chose these key ferroptosis-related DEGs for subsequent analyses: MAPK14, VEGFA, TGFBR1, and DUSP1." (PMID 36188533, 2022). "Activation of hypoxia-inducible factor 1 (HIF1) is a well-known cell response to hypoxic conditions induced by sepsis and LPS stimulation and HIF1 signaling was proposed to mediate VEGFA induction during Clostridium difficile infection." (PMID 31191497, 2019). "The results from a recent meta-analysis have demonstrated that VEGFA levels can also accurately predict sepsis mortality, with non-survivors presenting higher values." (PMID 37367740, 2023). "The VEGFA–VEGFR2 signaling pathway plays a key role in the activation of endothelial nitric oxide synthase (eNOS) and eNOS-mediated nitric oxide (NO) production, which has been found to be significantly reduced in sepsis." (PMID 36505401, 2022). "In addition, we constructed a Cox proportional hazard model using MAPK14, VEGFA, TGFBR1, and DUSP1: they influenced survival within 28 days in sepsis patients, which emphasizes their importance in sepsis pathogenesis." (PMID 36188533, 2022). "We identified four ferroptosis-related genes (MAPK14, VEGFA, TGFBR1, DUSP1) that may influence the pathological progression of sepsis and the resulting organ dysfunction." (PMID 36188533, 2022).
Sepsis (continued). "Levels of vascular endothelial growth factor A (VEGF-A), soluble fms-like tyrosine kinase-1 (sFlt-1) and angiopoietin (Ang) 1 and 2 were measured after the onset of neutropenic fever, in conditions designed to mimic the real-world use of a sepsis biomarker, based on our local practice." (PMID 23915833, 2013). "Also, the identified hub-gene signatures (e.g., NOS2, VEGFa, AKT, HO-1, SOD2) are useful for a deeper understanding of key signaling pathways-connection in sepsis development and may be helpful for early prediction of sepsis progression." (PMID 37407986, 2023). "Not all targets in the sepsis pathway are related to glycocalyx, and there are 6 targets (SI, ROCK1, TLR4, VEGFA, HPSE, and LGALS3) of active ingredients not only related to glycocalyx, but also involved in the sepsis pathway." (PMID 36062176, 2022). "No studies have shown that MAPK14, VEGFA, TGFBR1 and DUSP1 regulate ferroptosis in sepsis." (PMID 36188533, 2022).
retinopathy of prematurity (145 papers, 2008 to 2026). A bilateral retinopathy characterized by neovascularization, scarring, retinal detachment, and eventually blindness. "Our findings show that in the OIR model for retinopathy of prematurity, preventing EC apoptosis can accelerate revascularization of the retina and reduce the hypoxic stimulus that drives abnormal VEGFA expression." (PMID 32427589, 2020). "Pathologic ocular neovascularization in retinopathy of prematurity (ROP) and other proliferative retinopathies are characterized by dysregulation of vascular endothelial growth factor-A (VEGF-A)." (PMID 34285351, 2022). "Similar to the etiopathogenesis of retinopathy of prematurity (ROP), induction of hypoxia-inducible factor-1 α (HIF-1α) may be responsible for the production of vascular endothelial growth factor (VEGFA), which is the main cause of retinal neovascularization." (PMID 32848728, 2020).
renal carcinoma (142 papers, 2003 to 2026). A carcinoma arising from the epithelium of the renal parenchyma or the renal pelvis. "The hsa‐miR‐205‐5p enhances the chemosensitivity of renal carcinoma cells to 5‐FU and oxaliplatin by targeting Vascular Endothelial Growth Factor A (VEGFA) and modulating the PI3K/Akt signaling pathway." (PMID 40444136, 2025). "Angiogenesis is a prominent feature of renal cancer, with VEGFA recognized as a pivotal signaling molecule in regulating this process." (PMID 40274778, 2025). "They discovered two subgroups: VEGFA + SPP1 +, which is significantly overexpressed in renal cancer and linked to tumor angiogenesis and growth, and HLA-DR + CD74 +, which is present in renal cancer and contributes to antitumor immunity by activating T cells." (PMID 41035074, 2025). "Results suggested that CB-NPs can induce necrosis in renal carcinoma cells and tissues, downregulate VEGFA expression, promote renal carcinoma cell apoptosis, and reduce the polarization of M2 macrophages." (PMID 38375454, 2024). "Currently, sunitinib based on VEGFA/VEGFR target is the first line of treatment for advanced renal cancer." (PMID 31950034, 2019). "The present study aimed to determine HIF1A mRNA expression, the protein expression of HIF-1α and VEGF-A in the three most common histological types of renal cancer – ccRCC, pRCC, chRCC, as well as to analyze HIF1A and VEGFA differential gene expression and its influence on patient’s survival." (PMID 38053655, 2023). "This core was composed of several proteins with angiogenic functions in renal cancer including VEGFA, NRP1 and KDR (VEGF receptor-2), the latter of which may have predictive value in ccRCC." (PMID 29861861, 2018). "In addition to HMGB1 we investigated the expression levels of VEGFA, as a main target in renal cancer treatment strategies." (PMID 30123419, 2018). "Therefore, we explored whether HIF-1α/VEGFA/VEGFR signaling pathway influences the process by which AUY922 in-creases renal cancer sensitivity to sunitinib." (PMID 39149033, 2024). "By contrast, antibodies binding PlGF-2 or VEGFA to block NRP1 significantly reduced proliferation and migration of Caki-I kidney carcinoma cells in vitro, indicating this receptor mediates additional effects." (PMID 42001946, 2026). "Using Western blot analysis, we investigated the effect of AUY922 on the HIF-1α/VEGFA/VEGFR pathway by assessing the protein expression levels of HIF-1α, VEGFA, VEGFR1, and VEGFR2 in renal cancer cells." (PMID 39149033, 2024). "In a recent study found that up-regulation of miRNA-205-5p exerted an antitumor effect accomplished by decreasing VEGFA and inactivating PI3K/Akt/mTOR in renal carcinoma cells." (PMID 35669244, 2022). "Moreover, the frequency of VEGFA + mast cells is higher than that of TNF + cells, suggesting their role in promoting angiogenesis in renal cancer." (PMID 41035074, 2025). "Regarding renal cancer cells, the existence of the same hypoxic gradient did not exert any effect on the expression of VEGFA and EMAPII genes, and therefore, in the concomitant macrophage migration and polarization." (PMID 30788287, 2019). "TFEB/6p21/VEGFA-amplified RCC defined by the 6p21.1 chromosomal region is a rare and gradually recognized RCC subtype that exists independently of TFEB-translocated RCC and has been included in the molecularly defined renal cancer subtypes by the World Health Organization in 2022." (PMID 38730456, 2024).